TM9SF4 (transmembrane 9 superfamily member 4)
Description:
Associates with proteins harboring glycine-rich transmembrane domains and ensures their efficient localization to the cell surface. Regulates the assembly and activity of V-ATPase in colon cancer cells via its interaction with V-type proton ATPase subunit H (ATP6V1H) and contributes to V-ATPase-mediated pH alterations in cancer cells which play an important role in drug resistance and invasiveness of colon cancer cells. Plays an important role in an atypical phagocytic activity of metastatic melanoma cells called cannibalism and is involved in the pH regulation of the intracellular vesicles in tumor cells.
Synonyms: KIAA0255; dJ836N17.2
Tractability: Antibody: UniProt predicts a signal peptide or a membrane-spanning region. PROTAC: ubiquitination databases record sites on it; its protein half-life has been measured.
Gene: Protein-coding gene on chromosome 20 (32,109,714 to 32,167,258, forward strand). Ensembl gene ENSG00000101337.
Subcellular location: Membrane; Golgi apparatus; Early endosome
Gene Ontology:
Molecular function: cargo receptor activity; protein binding
Biological process: cell adhesion; Golgi to plasma membrane transport; phagocytosis; regulation of intracellular pH; response to hypoxia; vacuolar proton-transporting V-type ATPase complex assembly; protein localization to membrane
Cellular component: early endosome; Golgi apparatus; membrane
Genetic constraint (gnomAD): Loss-of-function variants: 26 observed, 95.81 expected, observed/expected ratio (o/e) 0.27, 90% interval 0.2 to 0.38. The upper end of that interval is the gene's LOEUF score, 0.38, which puts it in group 1 of 6, group 1 being the genes least tolerant of losing a copy. Missense variants: 549 observed, 876.46 expected, observed/expected ratio (o/e) 0.63, 90% interval 0.58 to 0.67. Synonymous variants: 293 observed, 333.16 expected, observed/expected ratio (o/e) 0.88, 90% interval 0.8 to 0.97.
Homologues: Orthologues: chimpanzee TM9SF4 (100% identical), dog TM9SF4 (99% identical), rabbit TM9SF4 (99% identical), pig TM9SF4 (98% identical), mouse Tm9sf4 (97% identical), rat Tm9sf4 (96% identical), guinea pig TM9SF4 (95% identical), macaque TM9SF4 (94% identical), tropical clawed frog TM9SF4 (88% identical), zebrafish tm9sf4 (85% identical), Drosophila melanogaster TM9SF4 (63% identical), Caenorhabditis elegans ZK858.6 (55% identical). Paralogues in human: TM9SF2 (44% identical), TM9SF3 (33% identical), TM9SF1 (31% identical).
Diseases named in the same sentence as TM9SF4 in open-access papers:
TM9SF4 is named in the same sentence as 23 diseases in open-access papers, as found by Europe PMC text mining. Sharing a sentence is not in itself a finding about the gene and the disease. The quoted sentences say what the papers report.
breast carcinoma (4 papers, 2021 to 2023). "TM9SF4 knockdown could enhance ER stress to sensitise chemoresistant breast cancer cells to drugs." (PMID 36639835, 2023). "In addition, studies in CRC and breast cancers have shown that high TM9SF4 expression may promote chemoresistance and that knocking down the gene is not only for inhibiting tumor progression but also for enhancing chemotherapeutic sensitivity." (PMID 35844556, 2022). "Immunoblot results showed that the endogenous protein expression level of TM9SF4 was much higher in ovarian cancer lines, including A2780, CaOV3, OVCAR3, COV362 and SKOV3, and breast cancer lines MCF-7 and T47D cells, than in noncancerous lines NIH3T3 and MCF-10A cells." (PMID 36175399, 2022).
colon cancer (4 papers, 2017 to 2025). "TM9SF4 is found to be upregulated in a variety of tumors, including melanoma, colon cancer cells, ovarian cancer cells, breast cancer, gastric cancer and gastrointestinal tumors." (PMID 40266427, 2025). "TM9SF4 is reportedly involved in the cannibalistic activity of metastatic melanoma cells and the resistance of colon cancer cells to chemotherapy by promoting the acidification of the tumor environment on the interior and exterior of the cell." (PMID 35655258, 2022). "In addition, the knockdown of TM9SF4 significantly reduces cell proliferation, migration and invasion of colon cancer and ovarian cancer cells." (PMID 40266427, 2025). "The downregulation of transmembrane 9 superfamily member 4 (TM9SF4), a positive regulator of V-ATPase activity, significantly inhibited tumor cell invasiveness and increased the cytotoxic effect of 5-FU in colon cancer cells." (PMID 33499187, 2021).
melanoma (3 papers, 2012 to 2022). A malignant, usually aggressive tumor composed of atypical, neoplastic melanocytes. "Then, TM9SF4 overexpression was observed in human malignant melanoma cells deriving from metastatic lesions and associated to the phenomenon of tumor cell cannibalism." (PMID 25961573, 2015). "Preliminary results clearly suggest that TM9SF4 is highly expressed on exosomes deriving from melanoma and ovary carcinoma patients, while TM9SF4 values in exosomes collected from healthy donors’ plasma are in the same range of background." (PMID 26082068, 2012). "We have recently shown that: (i) TM9SF4 is detectable is human melanomas, while it is undetectable in healthy skin tissues; (ii) in melanoma cells TM9SF4 localizes in early endosomal compartment and it is involved in the regulation of vesicles pH." (PMID 26082068, 2012).
ovarian carcinoma (3 papers, 2012 to 2025). A malignant neoplasm originating from the surface ovarian epithelium. "The migration and invasion abilities of control and TM9SF4 knockdown ovarian cancer lines, including A2780, SKOV3 and several high grade serous ovarian cancer lines (HGSOCs; CaOV3, OVCAR3 and COV362), were also investigated by the transwell assay." (PMID 36175399, 2022). "Knockdown of TM9SF4 reduces cell migration and invasion in ovarian cancer cells A2780, SKOV3 and several high grade serous ovarian cancer lines (HGSOCs)." (PMID 36175399, 2022). "(v) Knockdown of TM9SF4 increased cell adhesion and altered cell motility behavior of ovarian cancer cells A2780, SKOV3 and several HGSOCs." (PMID 36175399, 2022). "In athymic nude mice, knockdown of TM9SF4 completely abolished the ovarian cancer growth and metastasis, highlighting TM9SF4 as an attractive molecular target for ovarian cancer therapy." (PMID 36175399, 2022). "(vi) Knockdown of TM9SF4 nearly abolished the ovarian cancer growth and metastasis in athymic nude mice." (PMID 36175399, 2022). "Thus, we next explored possible role of TM9SF4 knockdown in ovarian cancer growth and metastasis in athymic nude mice." (PMID 36175399, 2022). "Importantly, TM9SF4 depletion completely abolishes the ovarian cancer metastasis in athymic nude mice." (PMID 36175399, 2022). "Therefore, the present study highlights an exciting possibility of targeting TM9SF4 or its related signaling pathway as a strategy for ovarian cancer treatment." (PMID 36175399, 2022). "Indeed, knockdown of TM9SF4 was found to change the cell movement patten from random walking behavior to directional motility behavior in A2780 cells, and reduce the transwell migration and invasion of multiple ovarian cancer cells." (PMID 36175399, 2022).
acute myeloid leukemia (2 papers, 2015 to 2024). Acute myeloid leukemia (AML) is a group of neoplasms arising from precursor cells committed to the myeloid cell-line differentiation. "TM9SF4, primarily involved in cell adhesion and innate immunity, is overexpressed in a small subset of patients with metastatic melanoma, acute myeloid leukemia, and myelodysplastic syndromes." (PMID 39185313, 2024). "However, TM9SF4 was found overexpressed in human metastatic melanoma and in a small subset of acute myeloid leukemia (AMLs) and myelodysplastic syndromes, consistent with an oncogenic function of this gene." (PMID 25961573, 2015).
colorectal cancer (2 papers, 2017 to 2025). A primary or metastatic malignant neoplasm that affects the colon or rectum. "Among these, TM9SF4, POFUT1 and KIF3B are all involved in the pathway of “Colorectal cancer”." (PMID 29108255, 2017).
hepatocellular carcinoma (2 papers, 2017 to 2025). A malignant tumor that arises from hepatocytes. "The transmembrane 9 superfamily protein member 4 (TM9SF4) is a transmembrane protein upregulated in multiple cancers; however, its role in hepatocellular carcinoma (HCC) remains unknown." (PMID 40266427, 2025).
myelodysplastic syndrome (2 papers, 2015 to 2024). A clonal hematopoietic disorder characterized by dysplasia and ineffective hematopoiesis in one or more of the hematopoietic cell lines. "As in malignant tumor cells, TM9SF4 mRNA was found overexpressed in a small subset of AMLs and myelodysplastic syndromes (MDS) characterized by the amplification of a chromosome 20 fragment (20q11.21) bearing the entire TM9SF4 gene." (PMID 25961573, 2015).
nasopharyngeal carcinoma (2 papers, 2025 to 2026). A carcinoma arising from the nasopharyngeal epithelium. "In nasopharyngeal carcinoma, TM9SF4 promotes tumor cell proliferation through affecting GUSBP11/miR-1226-3p/TM9SF4 axis." (PMID 40266427, 2025).
prostate carcinoma (2 papers, 2024). A carcinoma that arises from epithelial cells of the prostate gland. "For instance, TM9SF4 induces autophagy by suppressing mTOR phosphorylation, thereby enhancing anoikis resistance and metastatic potential in prostate cancer cells." (PMID 38460046, 2024). "In prostate cancer, circCEMI enhanced anoikis resistance by promoting transmembrane 9 superfamily member 4 (TM9SF4)‐mediated protective autophagy." (PMID 38332530, 2024).
metastatic cancers (1 paper, 2021). A carcinoma which has spread from the original site of growth to another anatomic site. "Future investigations on the expressions and roles of TM9SF4 and v-ATPase in CIC structures of metastatic cancers would shed novel lights on the CIC structure formation by tumor cell cannibalism." (PMID 34178655, 2021).
osteoporosis (1 paper, 2021). A condition of reduced bone mass, with decreased cortical thickness and a decrease in the number and size of the trabeculae of cancellous bone (but normal chemical composition), resulting in increased fracture incidence. "Furthermore, TM9SF4−/− mice show delayed bone loss and reduced lipid accumulation during ovariectomy-induced osteoporosis." (PMID 34774100, 2021). "The role of TM9SF4 in osteoporosis in vivo was further examined using an ovariectomy-induced osteoporotic mouse model." (PMID 34774100, 2021). "The results showed that ovariectomy-induced osteoporosis could be partially reversed by TM9SF4 knockout, as indicated by multiple bone mass-related parameters in micro-CT, including BV/TV, Tb.N and Tb.Sp." (PMID 34774100, 2021). "Our present study provides the first evidence that targeting TM9SF4 could be helpful for the prevention or treatment of osteoporosis." (PMID 34774100, 2021). "In future, it will be interesting to explore whether TM9SF4 could be a potential target for osteoporosis treatment." (PMID 34774100, 2021). "In mice, TM9SF4 knockout alleviates osteoporosis development in the ovariectomized mouse model." (PMID 34774100, 2021). "In addition, knockout of TM9SF4 reduced osteoporosis in ovariectomized mouse model." (PMID 34774100, 2021). "Therefore, we next explored the role of TM9SF4 in osteoporosis in vivo using ovariectomized mice." (PMID 34774100, 2021). "In the present study, we investigated the function of TM9SF4 in MSC differentiation commitment, as well as its role in osteoporosis." (PMID 34774100, 2021). "In ovariectomy-induced osteoporotic model, TM9SF4−/− mice retained higher bone mass and less lipid accumulation in trabecular bones, indicating an important role of TM9SF4 in the regulation of osteoporosis." (PMID 34774100, 2021).
ovarian tumor (1 paper, 2022). "Strikingly, TM9SF4 knockdown nearly abolished the ovarian tumor initiation/growth and metastasis in all three models in athymic node mice." (PMID 36175399, 2022).
tumor (12 papers, 2012 to 2025). "A recent study provided evidence that TM9SF4 is a V-ATPase-associated protein that modulates drug resistance and invasiveness of tumor cells." (PMID 25961573, 2015). "These include: (i) Knockdown of TM9SF4 in different types of tumor cells, which have a relatively high expression of endogenous TM9SF4, promoted actin stress fiber formation and increased the F-actin/G-actin ratio." (PMID 36175399, 2022). "In vivo, knockdown of TM9SF4 completely abolishes the tumor growth and metastasis in athymic nude mice." (PMID 36175399, 2022). "In the present study, we provide comprehensive evidence for the critical role of TM9SF4 in regulating F-actin dynamics and controlling tumor progression and metastasis." (PMID 36175399, 2022). "We observed that TM9SF4 is highly detectable on exosomes deriving from tumor cells while undetectable on in vitro cultured macrophages as well as healthy donors’ body fluids deriving exosomes." (PMID 26082068, 2012). "Presence of TM9SF4 on exosomes was evaluated by RT-PCR and Western blot analysis of exosomes deriving from different tumor cell lines highly expressing this protein." (PMID 26082068, 2012). "On the other hand, the expression of TM9SF4 is easy to obtain from IHC of tumor tissues." (PMID 40266427, 2025). "In addition, we verified the higher expression of TM9SF4 in tumor by IHC in tumor and normal tissue of 87 HCC patients from our clinical cohort." (PMID 40266427, 2025). "Taken together, TM9SF4 may promote tumor progression in HCC by influencing cell cycle and DNA damage repair-related pathways." (PMID 40266427, 2025). "Furthermore, immunostaining with TM9SF4 antibodies demonstrated that TM9SF4 expression was much higher in tumor than that in normal tissue." (PMID 36175399, 2022). "In sharp contrast, we could rarely observe any tumor formation in mice inoculated with TM9SF4 knockdown cells." (PMID 36175399, 2022). "TM9SF4 expression on vesicles of early-endosomal origin allowed us to hypothesize that this protein could be included in the tumor exosomes, forming, through a process of multivesicular fusion." (PMID 26082068, 2012). "Thus, TM9SF4 might play a role in maintaining an acidic tumor microenvironment in which metastatic tumor cells can survive and contribute to tumor metastasis." (PMID 37637068, 2023). "The Cancer Genome Atlas (TCGA), Genotype-Tissue Expression (GTEx) and International Cancer Genome Consortium (ICGC) databases were utilized to investigate the differential expression of TM9SF4 in HCC and tumor tissues." (PMID 40266427, 2025). "In both paired samples and unpaired samples of the TCGA-LIHC database, the expression of TM9SF4 was significantly higher in tumor tissues compared with normal tissues (P < 0.05)." (PMID 40266427, 2025). "Besides, we calculated various signatures covering tumor microenvironment, metabolic pathways, tumor intrinsic pathways via ‘IOBR’ packages and assessed their correlation with TM9SF4 expression." (PMID 40266427, 2025). "Strikingly, no metastatic tumor nodules could be observed following the injection of TM9SF4 knockdown cells." (PMID 36175399, 2022).
cancer (8 papers, 2012 to 2025). A tumor composed of atypical neoplastic, often pleomorphic cells that invade other tissues. "TM9SF4 is upregulated in various cancers and is often associated with poor prognosis." (PMID 40266427, 2025). "TM9SF4 is an evolutionarily conserved transmembrane protein that is functionally involved in phagocytosis, autophagy and cancer cell cannibalistic activity." (PMID 40266427, 2025). "TM9SF4 have been shown to play an important role in phagocytosis, autophagy and cancer cell cannibalistic activity." (PMID 40266427, 2025). "It is well documented that TM9SF4 plays important functional roles in phagocytosis of Drosophila hemocytes and cancer cell cannibalistic activity." (PMID 36175399, 2022). "In this study, we demonstrate the function of a protein named TM9SF4 in regulating actin dynamics and controlling cancer cell motility and metastasis." (PMID 36175399, 2022). "Together, this study provides evidence that TM9SF4 can facilitate the cofilin-mediated disassembly of F-actin by redox regulation, consequently regulating cancer cell migration in vitro and metastasis in mouse model in vivo." (PMID 36175399, 2022). "Here the authors show that TM9SF4 facilitates the cofilin-induced disassembly of F-actin to promote cancer cell migration and metastasis." (PMID 36175399, 2022). "Mechanistic studies showed that TM9SF4 facilitates the cofilin-induced disassembly of F-actin and that knockdown of TM9SF4 markedly inhibits cancer cell migration and invasion." (PMID 36175399, 2022). "Functional studies showed that TM9SF4 plays an important role in phagocytosis, autophagy and cancer cell cannibalistic activity." (PMID 36175399, 2022). "In order to quantify exosomal TM9SF4 level of expression in cancer patients, we are setting up a Double-sandwich ELISA test (ExotestTM) for quantitative and qualitative analysis of exosomes." (PMID 26082068, 2012). "The results showed that higher T stage, TNM stage, AFP levels and worse differentiation grade had greater TM9SF4 expression, which indicated that TM9SF4 expression may influence cancer development and metastasis." (PMID 40266427, 2025). "We first evaluated TM9SF4 expression in pan-cancer using data from TCGA and GTEx." (PMID 40266427, 2025). "The results showed that TM9SF4 was upregulated in various type of cancers, including HCC." (PMID 40266427, 2025). "Taken together, these data suggest that TM9SF4 is involved in cancer cell motility and migration." (PMID 36175399, 2022). "Moreover, a protein and a gene in common between cancer cells and amoebas have been described (TM9SF4) and recalled Tumor Cannibalism Associated Protein 1 (TUCAP-1)." (PMID 30854333, 2019). "TM9SF4 may interact with cofilin to regulate cancer cell migration and metastasis." (PMID 36175399, 2022). "TM9SF4 belongs to the TM9SF family and plays numerous roles in the development of various cancers." (PMID 40133271, 2025). "Because TM9SF4 can regulate F-actin dynamics, it is conceivable that TM9SF4 may influence actin-to-ERM connection, and thereafter regulate cell migration and cancer metastasis." (PMID 36175399, 2022). "The expressional level of TM9SF4 was compared among several cancer cell lines and noncancerous cell lines." (PMID 36175399, 2022). "A2780 and CaOV3 cancer cells with or without TM9SF4 knockdown were injected intraperitoneally followed by metastasis analysis in peritoneal cavity." (PMID 36175399, 2022). "It's remarkable that the function of V-ATPases in cancer was closely related to the wnt and notch signaling pathway, which indicateds to us that PLAGL2, POFUT1and TM9SF4 may cooperatively participated in the development human cancer." (PMID 29108255, 2017).
TM9SF4 also shares sentences with these, for which no sentence is quoted: metastatic melanoma (2 papers); bipolar disorder (1); colorectal adenocarcinoma (1); intrahepatic cholestasis (1); leukemia (1); rectal cancer (1); serous ovarian cancer (1); triple-negative breast carcinoma (1).